AR (androgen receptor)
Diseases named in the same sentence as AR in open-access papers (continued):
Sharing a sentence is not in itself a finding about the gene and the disease.
prostate (121 papers, 2007 to 2025). "For instance, in post-pubertal rats, exposure in utero has been linked to prostatitis, characterized by a decrease in androgen receptor (AR) activity and an increase in nuclear NF-κB levels." (PMID 39932461, 2025). "FOXA1, a pioneer factor that maintains epithelial identity and mediates AR cistrome engagement, has been previously implicated in prostate tumorigenesis and therapeutic resistance, particularly through mutations and enhancer reprogramming." (PMID 40643528, 2025). "The field has made major strides in defining the GAIN of function effects on the AR cistrome and transcriptional program associated with prostate tumorigenesis, including redistribution of AR to enhancers enriched for FOXA1 and HOXB13 motifs." (PMID 39672812, 2024). "Many recent findings demonstrated that YAP/TAZ and AR signaling serve as the central regulatory mechanisms for prostate tumorigenesis and several cancer-associated pathways can promote YAP/TAZ signaling." (PMID 33807895, 2021). "Aberrations of the AR signaling pathway are a hallmark of prostate carcinogenesis and thus therapies targeting AR have been the basis of PC treatments for many decades." (PMID 34769200, 2021). "Consistent with this idea, meta-analysis revealed that DNAH8 and AR-target gene expression were positively associated in prostate caner." (PMID 27363033, 2016). "Here, we investigated miRs regulated by the AR and their potential roles in regulatory networks underlying prostate malignancy." (PMID 27028864, 2016). "Pro-survival signaling mediated by the androgen receptor (AR) is implicated as a key contributor to prostate carcinogenesis, which classically controls PCa cell proliferation, survival, and differentiation." (PMID 23130941, 2012). "Abundant evidence demonstrated that androgens and the androgen receptor are associated with the development and progression of prostate pathogenesis." (PMID 21274285, 2011). "Nevertheless, several lines of evidence showed the association between estrogens and prostate carcinogenesis through a number of mechanisms such as receptor mediation, genotoxic effects of estrogen metabolites, bypassing the AR signaling pathways, or androgen aromatization to estrogens." (PMID 38612439, 2024). "Also, HMGB1 may regulate AR either by acting as a co-activator of AR or indirectly associating with RAGE signaling in prostate oncogenesis." (PMID 31410208, 2019). "Thus, HMGB1 may regulate AR either by acting as co-activator of AR or indirectly associating with RAGE signaling in prostate oncogenesis." (PMID 23766911, 2013). "Understanding the molecular mechanisms of prostate carcinogenesis has led to the development of therapeutic strategies targeting AR." (PMID 41264145, 2025). "This highlights a shared mechanism between germline and somatic alterations, emphasizing the pivotal role of AR signaling in prostate tumorigenesis." (PMID 41468516, 2025). "Common genetic alterations, including FOXA1 mutations, gain of the androgen receptor gene (AR amplification or mutation), and structural variants such as loss of NKX3.1 (8p21) and PTEN (10q23), account for prostate carcinogenesis." (PMID 38483933, 2024). "ARD1 is upregulated by androgen in an AR-dependent manner in PCa and found to be critical for transcriptionally activating AR target genes that are involved in prostate tumorigenesis, both in vivo and in vitro." (PMID 38275816, 2024). "Given that VPC-14228binds to the DNA binding domain shared between wild-type full-lengthAR as well as its truncation mutants, we first tested this degraderfor wild-type AR degradation in AR-sensitive LNCaP prostate cancercells." (PMID 37252349, 2023). "Sulforaphane has been proposed to prevent prostate carcinogenesis by disrupting the AR signaling pathway." (PMID 37108142, 2023). "The androgen receptor is known for its role in the development and function of a normal prostate, but it is also an essential driver of prostate tumorigenesis." (PMID 37176106, 2023).
prostate (continued). "Prostate carcinogenesis is usually initiated by androgen receptor (AR) signaling, and proliferation of cancer cells is promoted by a preferential increase in aerobic glycolysis." (PMID 37108142, 2023). "Previous work has demonstrated that AR-DNA binding is systematically and consistently reprogrammed during prostate tumorigenesis and disease progression." (PMID 35509021, 2022). "Identifying the regulation of stromal AR in IGFBP3 expression in Gli1-lineage FB is intriguing, suggesting an underlying mechanism for androgen-mediated IGF1 signaling activation in prostate oncogenesis." (PMID 36323713, 2022). "Given its involvement in modulating AR signaling and prostate disease pathology, TIP60 has emerged as a potentially useful but challenging therapeutic target." (PMID 36060957, 2022). "Our finding of hARtg to activate IGF1R axes in atypical basal cells explores a mechanism for AR's oncogenic role in prostate oncogenesis." (PMID 35902588, 2022). "In this study, using in vivo tissue recombination assays and newly generated mouse models, we examined if stromal AR signaling in Gli1-lineage cells acts as tumor niches in prostate oncogenesis." (PMID 36323713, 2022). "Previous studies demonstrated the involvement of the AR signaling axis in tumorigenesis of various types of cancers, including prostate, ovary, bladder, lung, liver, and kidney malignances." (PMID 36013056, 2022). "Androgen receptor (AR) is an important mediator of prostate gland growth and development, which is vital for prostate carcinogenesis and PC progression." (PMID 33499881, 2021). "IL6 was reported to modulate progression, differentiation, survival, and angiogenesis of PCa, moreover it was shown to mediate AR activation in benign and malignant prostate models." (PMID 34822550, 2021). "Because our observations implicate a role for the POP3 protein in aging-related prostatic inflammation, further work will be needed to examine the role of androgen-AR/POP3/AIM2 axis in the development of aging-related prostatic diseases." (PMID 33923931, 2021). "This is consistent with enhanced chromatin binding of AR itself in AR-overexpressing PC tumors, as well as the reprogrammed chromatin binding of other TFs during prostate carcinogenesis and progression." (PMID 34283056, 2021). "Prostate cancer-associated non-coding RNA 1 (PRNCR1) is a lncRNA that has been proposed to contribute to prostate carcinogenesis by increasing the looping of androgen receptor (AR)-bound enhancers to AR target genes and, in turn, increasing cell proliferation." (PMID 33374332, 2020). "E. coli strains are known prostatitis-related microbes, which is consistent with their abundance being positively correlated with increased AR expression." (PMID 32899474, 2020). "ER-α is also expressed by cancerous prostate cells, while, respectively to estrogens, androgens are the male sex hormones that bind to androgen receptors (AR) and are expressed during all stages of prostate carcinogenesis and related to hereditary PC." (PMID 32847060, 2020). "The alteration of this gene has been previously implicated in the PC development and is known for regulating AR transcriptional activity during prostate tumorigenesis." (PMID 32630240, 2020). "TLE3 was shown to co-localize with FOXA1 and AR at enhancer elements, which are selectively activated during prostate tumorigenesis, underscoring the importance of these transcription factors in this context." (PMID 31855178, 2019). "UXT can interact with the N terminus of AR and facilitate receptor dependent transcriptional activation, which contributes to its role in AR-dependent prostate tumorigenesis." (PMID 31481081, 2019). "In this study, we unveil key elements of the crosstalk between the AR and the Hippo signaling pathways and its implications for prostate carcinogenesis." (PMID 29383141, 2017).
prostate (continued). "Examples of such factors include the androgen receptor (AR), a TF involved in normal prostate development which becomes reprogrammed during prostate carcinogenesis." (PMID 29312534, 2017). "Prostate carcinogenesis and progression therefore seem to involve acquisition of autocrine growth signals in addition to a switch of the AR from being a cell intrinsic inhibitor of proliferation to becoming a stimulator of proliferation." (PMID 27378372, 2016). "The androgen receptor (AR), a member of the large family of nuclear receptors (NRs), plays a critical role in prostate carcinogenesis through the regulation of transcriptional networks, genomic stability, and gene fusions." (PMID 27323416, 2016). "Androgen receptor (AR) signaling is crucial to the development and homeostasis of the prostate gland, and its dysregulation mediates common prostate pathologies." (PMID 27203692, 2016). "Taken together, these data provide additional line of evidence demonstrating that the promotional effect of transgenic AR protein in BBN-induced bladder tumorigenesis is mediated through androgens." (PMID 26862755, 2016). "The ability of miR137 to modulate AR signaling supports miR137 as a potential therapeutic target for preventing or delaying prostate carcinogenesis and progression." (PMID 26461474, 2015). "Immunocytochemistry, western blot, and affinity-purification analyses were used to study how androgens influenced the expression, subcellular localization, and function of CXCR7, CXCR4, and androgen receptor (AR) in LNCaP prostate-tumor cells." (PMID 25884570, 2015). "Let-7c was found to be inversely correlated with the AR in cell culture, xenografts of prostate mouse models, and human PC specimens, whereas the expression of Lin28, a master regulator of let-7 miRNA processing, is correlated positively with AR expression." (PMID 26690121, 2015). "Our results suggest that ELK1 plays an important role in bladder tumorigenesis and cancer progression, which is further induced by AR activation." (PMID 26342199, 2015). "Nonetheless, it would be worthwhile to establish the role of specific miRNAs in the fine-tuning of AR expression in prostate carcinogenesis." (PMID 26877888, 2013). "SUMOylation regulates the activity of prostate carcinogenesis through a variety of mechanisms, some of which are unrelated to AR signaling." (PMID 24970135, 2012). "Among divergent transcription factors regulated by SUMOylation and deSUMOylation, the androgen receptor (AR) is of exceptional significance, given its established role in prostate carcinogenesis." (PMID 24970135, 2012). "During prostate carcinogenesis, both AR-independent and AR-dependent signaling mechanisms contribute to the malignant transformation of epithelial cells." (PMID 20628607, 2010). "It is well known that androgenic hormones and AR both have critical roles in normal prostate development function and in most prostate diseases, including CaP." (PMID 19844236, 2009). "A very low expression was observed for the TMEPAI gene, which is involved in androgen receptor signaling, and is proposed to play a role in prostate tumorigenesis." (PMID 18827820, 2008). "In epithelial cells, AR depletion induces inflammation, leading to prostate carcinogenesis." (PMID 40007149, 2025). "Prostate carcinogenesis is primarily driven by androgen receptor (AR) signaling." (PMID 39859392, 2025). "Multiple studies revealed AR was expressed in normal human breast and breast cancer tissue." (PMID 41282089, 2025). "Measuring the expression of AR and SYN in human PCa and TripleTg mouse prostate PCa tissues showed significant reduction of nuclear AR expression in both PCa cells in human tissues isolated from patients treated with ABI and ENZ and Solid-PCa cells from TripleTg mice." (PMID 38336745, 2024).
prostate (continued). "DHT binds to the androgen receptor with high affinity, and this complex initiates transcription and ultimately controls the regulation of the prostatic cell cycle, cell growth, and differentiation, contributing to prostatic disease progression." (PMID 39204137, 2024). "The presence of AR is also critical for prostate carcinogenesis and therapeutics." (PMID 36835012, 2023). "Androgen receptor (AR) signaling mediates the initial stages of prostate carcinogenesis." (PMID 37108142, 2023). "In addition, EZH2 acts as a transcriptional activator to activate androgen receptor (AR) gene transcription by directly occupying its promoter to promote prostate carcinogenesis." (PMID 36313363, 2022). "Similarly to SMARCD1, we found that numerous downstream targets of SMARCD2 (e.g., PTGR1, TRMP8, PGC) and SMARCD3 (e.g., EGF, PIK3AP1, HSD3B1) were AR-driven genes that are involved in prostate tumorigenesis, progression and metastasis." (PMID 36611918, 2022). "MAGE-A11 contributes to the AR signaling pathway in prostate cancer cells." (PMID 35022469, 2022). "Androgens and androgen receptor (AR) signaling drive prostate carcinogenesis." (PMID 34031488, 2021). "Moreover, AR directly upregulates G3BP1 transcription to further amplify G3BP1-SPOP signaling in a feed-forward manner and potentiates AR signaling and promote prostate tumorigenesis." (PMID 34795264, 2021). "Androgen receptor (AR) signaling is critical for prostate carcinogenesis." (PMID 33292604, 2020). "Factors other than androgen-AR interactions are involved in prostatic diseases." (PMID 28196103, 2017). "Androgen/AR signaling is very crucial in the onset and progression of prostate carcinogenesis." (PMID 25860954, 2015). "Promotes prostate carcinogenesis through reciprocal communication with AR." (PMID 26110379, 2015). "Specifically, these results suggest that studying long noncoding RNAs and AR-mediated signaling pathways may provide a better understanding of prostate carcinogenesis." (PMID 26110379, 2015). "Most of these genes also play important roles in AR mediated Prostate carcinogenesis." (PMID 26877888, 2013). "Among its client proteins are transcription factors, cell cycle regulators, signaling kinases, mediators of apoptosis as well as steroid hormone receptors, such as the androgen receptor (AR), which have critical role in prostate carcinogenesis and in the progression to HRPC." (PMID 24130883, 2013). "The mechanism of DDC-mediated regulation of AR signaling in prostate carcinogenesis remains unknown, but may involve sensitization of AR to limiting concentration of androgen." (PMID 17553164, 2007). "Here, in an effort to better understand the molecular function of DDC as a coactivator of AR-mediated signaling and to identify novel targets of prostate carcinogenesis, we evaluated the effects of regulated DDC expression in an inducible manner in LNCaP cells using gene microarray analysis." (PMID 17553164, 2007). "For instance, the target protein Androgen Receptor (AR) has a relatively strong interaction with 62 active molecules, implying the multi-component characteristics of herbs and indicating the significant effects of PCa-herbs in the directly controlling prostate carcinogenesis." (PMID 36795572, 2023). "It is also worth noting that despite the earlier observation of in vitro activation of the AR by growth factors, including members of the FGF family, whether aberrant FGFR signalling may contribute to prostate carcinogenesis via ligand-independent activation of AR remains unclear." (PMID 21952621, 2011). "Investigation of the transcription factors (TFs), such as the androgen receptor and its co-regulators FOXA1 and HOXB13, known to be important in prostate tumorigenesis, revealed their involvement in the differential expression of these genes." (PMID 40525903, 2025).
prostate (continued). "Previous work from our lab and others demonstrated that antagonism of hormone receptors, notably the androgen receptor, results in radiosensitization of AR+ TNBC33–35 and prostate cancer." (PMID 35273179, 2022). "The aberrant activations of AR and TGF-β signaling executed critical functions in malignant growth of prostate and cancer metastasis." (PMID 32064040, 2020). "The effect was also observed in rat prostate BPH treated PRE-HIF, strongly indicating the potential effects of PRE-HIF on AR signaling modulation." (PMID 32093357, 2020). "Khalili M etal found a significant decrease in AR expression in infected prostate glands by preparing a bacterial prostatitis model, and very low TNF-α and IL-1β exposure can also lead to inhibition of the androgen receptor pathway." (PMID 31372097, 2019). "ESR2 is regulated by AR and interacts with ESR1 to regulate prostate carcinogenesis through the modulation of genes involved in cell proliferation and apoptosis." (PMID 31523634, 2019). "Here, the authors show that androgen receptor directly transactivates LRIG1 which then antagonises ERBB signalling and c-Myc expression to inhibit prostate tumorigenesis." (PMID 31792211, 2019). "In prostate disease BPH, macrophage-secreted CCL3 was downstream target of androgen receptor (AR), which is also secreted by macrophages, to promote prostate stromal cell proliferation." (PMID 29769604, 2018). "Here we used the NOD mouse model with spontaneous autoimmune prostatitis to examine the potential roles of androgen receptor (AR), the key regulator of PSA signaling, in the prostatitis that involved the infiltrated T cells." (PMID 27564257, 2016). "In this study, we demonstrated that infiltrated CD4+ T cells play important roles in prostatitis by using NOD mice which can be rescued by ASC-J9®, the newly developed AR degradation enhancer." (PMID 27564257, 2016). "However, AR knockout NOD mice might be better materials to clarify AR role in prostatitis." (PMID 27564257, 2016). "Taken together, our findings identify a regulatory mechanism by which AR upregulates KLF4 expression directly and transcriptionally; subsequently, KLF4 increases miR-1 expression levels and sustains suppressed prostate tumorigenesis." (PMID 27991915, 2016). "The HMG domain of WHSC1 can interact with the DNA-binding domain of the androgen receptor (AR) and, in the presence of the ligand, enhances AR-mediated transcriptional activation, thereby implicating WHSC1 in the promotion of prostate carcinogenesis." (PMID 26092122, 2015). "Some stem cell markers were found as highly expressed in AR-negative basal epithelial cells from benign prostate tissue and low in luminal tumoral cells, in a similar pattern to the one we observed for KRT7." (PMID 35406395, 2022). "In prostate carcinogenesis, androgens are known to control the expression of the transient receptor potential melastatin 8 (TRPM8) protein via activation of androgen receptor (AR)." (PMID 31501416, 2019). "In addition, results of RWPE-1 and WPMY-1 cells showed that HBX-5 inhibited the over-expression of AR and PSA in DHT-induced prostate hyperplastic microenvironments." (PMID 30322186, 2018). "The ERα-NEAT1 axis is functional both in AR-positive and -negative cell lines, and drives prostate carcinogenesis." (PMID 25415230, 2014). "Despite that, the function of Cdc25B to AR is independent of its cell cycle function; Cdc25B is proposed to play a role in human prostate carcinogenesis." (PMID 23637932, 2013). "Moreover, the AhR acts as an E3 ligase of the AR and AhR null TRAMP mice show increased prostate tumorigenesis." (PMID 20140206, 2010). "Thus, analysis of transformation by the TE fusion gene expression in the absence of AR activity is relevant to prostate carcinogenesis in vivo." (PMID 29581856, 2018).